TNF (tumor necrosis factor)
Diseases named in the same sentence as TNF in open-access papers (continued):
Sharing a sentence is not in itself a finding about the gene and the disease.
scrub typhus (continued). "By using neutralizing antibody in vivo and genetically modified mice, we provide strong evidence that TNF-TNFR signaling is required for boosting host immunity and controlling bacterial growth during scrub typhus." (PMID 35479068, 2022). "The percentages of IFN-α+ and TNF-α+ pDCs were found to be significantly lower in scrub typhus patients than in HCs (for IFN-α+ cells, median 1.0% versus 23.2%, P = 0.001; for TNF-α+ cells, median 2.8% versus 22.0%, P = 0.005)." (PMID 34276693, 2021). "After reproducing the pro-inflammatory milieu using a cytokine cocktail including IFN-γ, IL-12, and TNF-α, we observed the dynamics of CD86 and CD274 expression patterns in pDCs and cDCs, which was similar to our data in scrub typhus patients." (PMID 34276693, 2021). "Markers (TNF-α level, CRP level, WBC count, and modified APACHE II score) were compared across deceased patients and those with severe and mild scrub typhus." (PMID 30909868, 2019). "The low levels of TNF-α and IL-1β observed upon admission appear to be consistent with a previous study in Vietnam, where TNF-α and IL-1β levels in scrub typhus patients were undetectable in 90% and 75%, respectively." (PMID 22192733, 2012). "In addition, the production of interferon (IFN)-α and tumor necrosis factor (TNF)-α by circulating pDCs, and interleukin (IL)-12 and TNF-α by circulating cDCs was reduced in scrub typhus patients." (PMID 34276693, 2021). "To determine whether impaired TNF-α production by MAIT cells is related to PD-1, we examined the expression levels of PD-1 in the peripheral blood samples of 17 scrub typhus patients and 14 HCs." (PMID 27463223, 2016). "We also observed increased polyfunctionality in T cells when compared to unstimulated controls and this consisted of the triple (IFN-γ+TNF+IL-2) and double (IFN-γ+TNF) positive CD4+ T cell but not CD8+ T cells during acute infection of patients with scrub typhus." (PMID 36961865, 2023). "It is known that CD44+ activated T cells may contribute to controlling bacterial growth through production of cytokines (e.g. IFN-γ and TNF-α) and granules (granzyme B), and that decreased CD4+ T cell numbers observed in acute scrub typhus patients is likely due to increased cell apoptosis." (PMID 35479068, 2022). "However, to our knowledge, no research had been conducted to examine the serum TNF-α concentration of patients who died of scrub typhus and research on other predictors of disease severity is insufficient." (PMID 30909868, 2019). "However, serum TNF-α levels in patients who die of scrub typhus have never been assessed." (PMID 30909868, 2019).
tauopathy (19 papers, 2016 to 2026). Neurodegenerative disorders involving deposition of abnormal tau protein isoforms (tau proteins) in neurons and glial cells in the brain. "The LOAD mice also display higher blood concentrations of proinflammatory cytokines tumor necrosis factor alpha (TNF‐α) and interleukin (IL)‐10, as well as neurofilament light chain, hence more accurately mimicking human tauopathies and AD." (PMID 40420360, 2025). "Neuroinflammation can amplify itself by increasing tauopathy and Aβ deposition through inflammatory cytokines such as IL-1β, IL-6, and TNF-α." (PMID 36389075, 2022). "Overall, the data presented in this in vivo study in the PS19 mouse model of tauopathy are the first to report significant therapeutic effects of biologic TNF-α inhibitors on Aβ-independent tau pathology following systemic administration." (PMID 34972522, 2021). "Further, neuroinflammation can amplify itself by increasing tauopathy and Aβ deposition through microglia-secreted pro-inflammatory cytokines such as IL-6 and TNF-α." (PMID 33059746, 2020). "Proteinopathies, such as amyloidopathy and tauopathy, oxidative stress, metabolic impairments and higher levels of proinflammatory cytokines such as tumor necrosis factor alpha (TNF-α), interleukin-1β (IL-1β), IL-6, IL-8, and IL-10 in the brain, are associated with AD." (PMID 38275641, 2023). "Future work replicating these findings in other models of tauopathies and models combining Aβ and tau pathology may yield important preclinical data supporting the use of biologic TNF-α inhibitors for AD and other tauopathies." (PMID 34972522, 2021). "Unfortunately, no studies have truly tested the effects of TNF-α signaling in pure tauopathy models despite TNF-α being implicated in activating pathways involved in tau pathogenesis such as caspase 1 as well as p38-MAPK and JNK kinases." (PMID 28662669, 2017). "Future studies are needed to fully understand the role of TNF-α in tauopathy-driven neurodegeneration and whether it is a viable drug target to slow disease progression." (PMID 28662669, 2017). "While AMI treated P301S mice demonstrated significant decrease in the levels of MYD88, NF-KB, TNF-α and IL-22 by 52% (P < 0.0001, F = 770.9), 54% (P < 0.0001, F = 794.5), 49% (P < 0.0001, F = 385.6) and 39% (P < 0.0001, F = 668.8) respectively when compared to tauopathy model." (PMID 41484454, 2026). "Furthermore, the ameliorating effect of the TNFα inhibitor etanercept on oTau-facilitated LTD lends support to the therapeutic potential of targeting inflammatory pathways to mitigate synaptic dysfunction in early tauopathies." (PMID 40251677, 2025). "In addition, the LC exhibited exaggerated expression of pro- and anti-inflammatory mediators (IL-6, TNFα, inducible nitric oxide synthases 2 (iNOS2), and interleukin 10 (IL-10)) in transgenic rats suggesting that tauopathy affects also the immune background in LC." (PMID 26792515, 2016). "Concordantly, CST reduced expression of CD68, GFAP, IL-6, TNF-α, CXCL1, and CXCL10, extending its known peripheral anti-inflammatory actions 20,38 to the central nervous system and establishing CST as a regulator of neuroimmune homeostasis in Tauopathy." (PMID 41509358, 2026).
upper respiratory tract infections (19 papers, 2015 to 2026). "JAK inhibitors also increase the risk of upper respiratory tract infection, and the rate of herpes zoster virus infection is higher than TNF inhibitors." (PMID 37485474, 2023). "These therapies, including TNF-α inhibitors, although highly effective, can produce profound immune suppression and predispose patients to common upper respiratory tract infections as well as reactivation of cell mediated controlled infections." (PMID 28086756, 2017). "TNF inhibitors can cause upper respiratory tract infection, cytopenia, and elevated liver enzymes." (PMID 37485474, 2023). "reduce IFNγ & TNF-α and increase IL-4 & IL-10 secretions to control the immunostimulatory effects in upper respiratory tract infection." (PMID 39294611, 2024). "Common adverse effects of all TNF-α inhibitors include nasopharyngitis, upper respiratory tract infections, and infection site reactions." (PMID 34884596, 2021). "Though the exclusion criteria were strictly followed, it can be suggested that these patients would have had a local trauma, aphthous ulcer, upper respiratory tract infection, or any other subclinical infection in the recent past for having high levels of TNF-α in saliva and serum." (PMID 25861271, 2015). "Vitamin D supplementation in patients with IBD reduces inflammation and the risk of clinical relapse, improves responsiveness to anti-TNF therapy, prevents upper respiratory tract infections in winter and spring, and may have a positive effect on mental health." (PMID 37077923, 2023). "Outcomes included reactive oxygen species (ROS; whole-blood EPR), total antioxidant capacity (FRAP), superoxide dismutase (SOD), interleukin-6 (IL-6), tumor necrosis factor-α (TNF-α), and upper respiratory tract infection (URTI) incidence and duration." (PMID 42197007, 2026). "In our earlier meta-analysis of the effectiveness of probiotic supplementation on the upper respiratory tract infection (URTI) and inflammatory markers in elite athletes, we concluded that probiotic supplementation may decrease IL-6 and TNF- levels." (PMID 35807826, 2022).
urinary tract infection (19 papers, 2009 to 2025). "Surgery spreads the primary urinary tract infection, causing excessive release of a large number of inflammatory cytokines (such as IL-6, IL-8, and TNF-α)." (PMID 34422076, 2021). "One patient experienced a urinary tract infection during the second month of anti-TNFα treatment, caused by Escherichia coli." (PMID 26832154, 2016). "When the body is infected with bacteria, such as a urinary tract infection, the immune system releases TNF-α to promote an inflammatory response." (PMID 41357523, 2025). "On the other hand, previous studies have noted that patients with chronic SCI tend to exhibit reduced levels of TNFα than HCs, especially those presenting with accelerated immunosenescence after repeated urinary tract infections." (PMID 37108209, 2023). "Therefore, elevated levels of TNF-α in patients after ICH can be viewed as an immune response to urinary tract infection, a response designed to fight infection but also a marker of the presence of infection." (PMID 41357523, 2025). "KEGG analysis indicated that urinary tract infections likely involve the TNF-αsignaling pathways." (PMID 34592898, 2021). "These may include prompt treatment of disease conditions that are associated with release of inflammatory cytokines including the TNF-α e.g. urinary tract infection." (PMID 31448006, 2018). "The hs-CRP in the serum of children with urinary tract infection was 98.21±19.27 mg/mL, and the values of PCT, IL-6, TNF, and IFN-γ were 4.713±1.488 ng/mL, 422.7±160.0 pg/mL, 1.908±0.1966 pg/mL, and 37.22±15.05 pg/mL, respectively." (PMID 37534327, 2023).
carotid atherosclerosis (18 papers, 2007 to 2026). A thickening and loss of elasticity of the walls of carotid arteries that occur with formation of atherosclerotic plaques. "Furthermore, its overabundance has already been reported in patients with carotid atherosclerosis and cardiovascular disease, and has been associated with TNF‐alpha production." (PMID 36287108, 2023). "This research shows that high levels of TOS, LHP, 8-IP, MDA, MCP-4, AA, hs-CRP, and TNF-α are associated with severe coronary and carotid stenosis suggesting a possible roles of oxidative stress and inflammatory mediators in the development of coronary and carotid atherosclerosis." (PMID 34976297, 2021). "Among these, IL-6 and TNF-α are key pro-inflammatory cytokines involved in all stages of carotid atherosclerosis—from plaque formation and progression to rupture." (PMID 40963681, 2025). "Numerous studies have shown that inflammatory factors [tumor necrosis factor alpha, interleukin (IL)-1, and IL-6 levels] are elevated in patients with atherosclerotic heart disease." (PMID 37476576, 2023). "A study on carotid atherosclerosis showed that blood levels of IL-6 and TNFα were higher in patients with carotid atherosclerosis compared to control subjects and the cytokine levels increased with increasing amounts of carotid atherosclerosis stenosis." (PMID 35600479, 2022). "Other prospective observations suggest that subclinical carotid atherosclerosis progression in RA is potentially modified favourably by TNF inhibitors." (PMID 22390577, 2012). "Salivary TNF-α levels were significantly elevated in patients with carotid atherosclerosis." (PMID 41913845, 2026). "TNF inhibition also improves endothelial function and arterial stiffness and might also stabilize carotid atherosclerosis." (PMID 38542402, 2024). "IL-23 accentuated tumor necrosis factor release in monocytes from patients with carotid atherosclerosis, and high plasma levels of IL-23 may increase mortality." (PMID 36720935, 2023). "Inflammatory cytokines such as interleukin-6 (IL-6), tumor necrosis factor-α, and hs-CRP are well-established markers of carotid atherosclerosis." (PMID 24192205, 2013).
dental caries (18 papers, 2013 to 2025). The decay of a tooth, in which it becomes softened, discolored, and/or porous. "A meta-analysis was performed using a random-effects model to evaluate the association between dental caries/health, and the concentration of TNF-α, IL-6 and IL-8." (PMID 39026257, 2024). "In this study, we utilized the inflammatory cytokine Tumor Necrosis Factor alpha (TNFα), which is known to be elevated in patients with dental caries and plays a central role in coordinating various cellular signaling events." (PMID 39868289, 2025). "The meta-analysis revealed that there are significant differences between the levels of IL-6 and TNF-α in saliva of children with active dental caries compared to their control groups." (PMID 39026257, 2024). "Elevated values of pro-inflammatory cytokines IL-6, IL-8, and TNFα in saliva are found in people with dental caries and chronic stomatitis." (PMID 39684489, 2024). "Previous studies have shown that salivary IL-6 levels decrease with improved oral hygiene, supporting earlier findings that cytokines like tumor necrosis factor-alpha (TNF-α), IL-6, and interleukin-8 (IL-8) are closely associated with the progression of dental caries." (PMID 40002706, 2025). "The findings suggest that IL-6 and TNF-α levels may have potential as complementary biomarkers for assessing dental caries severity." (PMID 39026257, 2024). "Dental caries or trauma can result in an inflammatory response, characterized by an accumulation of inflammatory cells, which release host proinflammatory cytokines, including tumor necrosis factor-α (TNF-α) and interleukins." (PMID 25427002, 2014). "In the background of dental caries, the effects of several cytokines have been hypothesized, in which IL-1β and TNFα play a central role, because their up-regulation was demonstrated in the odontoblast layer on the surface of carious teeth by in vitro and in vivo experiments." (PMID 38334643, 2024). "By producing and secreting TNF-α, IL-1, and CXCL8, immature dendritic cells (DC) contribute to the immune response of human dental pulp to oral pathogens entering dentin during dental caries." (PMID 37179325, 2023).
Disseminated intravascular coagulation (18 papers, 2008 to 2025). Disseminated intravascular coagulation is characterized by the widespread activation of coagulation, which results in the intravascular formation of fibrin and ultimately thrombotic occlusion of small and midsize vessels. "Also, higher TNF-α level was associated with higher occurrence of disseminated intravascular coagulation and mortality." (PMID 28469676, 2016). "Our results of elevated IL-10/TNF-α and decreased IP-10/IL-10 ratios are similar to other studies looking at septic neonates with disseminated intravascular coagulation (DIC)." (PMID 32407417, 2020). "Moreover, IL-6 contributes to the hypercoagulability status together with TNF-α and IL-1, a phenomenon which, if accompanied by severe inflammatory syndrome, leads to disseminated intravascular coagulation." (PMID 37834356, 2023). "The serum levels of IL-6, TNF-α and serum CCHFV titer at admission were significantly and positively correlated with disseminated intravascular coagulation (DIC) scores (r = 0.626, p = 0.0002; r = 0.461, p = 0.009; and r = 0.625, p = 0.003, respectively)." (PMID 25066751, 2014).
enterocolitis (18 papers, 2013 to 2026). An inflammatory process affecting the small intestine and colon. "Meanwhile, it was reported that IBD patients have reduced levels of butyric acid in their feces, accompanied by elevated levels of IL-1β and TNF-α, suggesting that the mice in the high-dose group were at high risk of developing enterocolitis." (PMID 40565727, 2025). "However, a deficiency in both IL-10 and TNF-α exacerbates enterocolitis in mice, indicating some protective effects of TNF-α on this condition." (PMID 34675913, 2021). "We selected adalimumab for treatment because anti–TNF‐α therapy is widely used as a first‐line biologic treatment in monogenic or genetically determined enterocolitis when sustained mucosal inflammation or steroid dependence is present." (PMID 41426201, 2026). "For these studies, we measured a key pro-inflammatory cytokine (TNF-α) previously shown to be upregulated in intestinal biopsies of dogs and humans with enterocolitis." (PMID 38067065, 2023). "There are multiple potential translational implications for the findings that LTα3 and MyD88 contribute to TNF-independent intestinal damage in this model of severe enterocolitis." (PMID 35077396, 2022). "TNBS-induced enterocolitis was found to reduce villus length, enlarge crypts, decrease peristalsis, increase the number of goblet cells, and increase the expression of tumor necrosis factor-α." (PMID 28961226, 2017). "Enterocolitis is a common irAE, currently managed with corticosteroids and, if necessary, anti-tumor necrosis factor-α therapy." (PMID 28204866, 2017). "The increase of articular TNF-α observed in animals suffering enterocolitis (EC group) was abrogated by the consumption of LCFM prior to S. Enteritidis infection (L. casei + EC group)." (PMID 24340048, 2013). "Our studies demonstrate that the synbiotic GWT improves the pathophysiology of chemically induced enterocolitis, which may be attributable in part to the inhibition of TNF-α and IL-12 production." (PMID 29862296, 2018). "During enterocolitis intestinal TNF-α is 7 times higher than in animals without S. Enteritidis infection (Control and L. casei + Strep groups); similarly, IL-17 and IL-23 are significantly elevated (11 and 5 times higher compared to controls, respectively)." (PMID 24340048, 2013).
Fanconi anemia (18 papers, 2012 to 2025). Fanconi anemia (FA) is a hereditary DNA repair disorder characterized by progressive pancytopenia with bone marrow failure, variable congenital malformations and predisposition to develop hematological or solid tumors. "Analysis of the evolved copy-number genotypes implicated an increase in the PI3K-Akt pathway and decreases in the Fanconi-anemia pathway, RNA degradation, Notch signaling, and TNF signaling, mimicking pathways impacted in human serous ovarian cancer." (PMID 31923184, 2020). "Overexpression of TNFα could contribute to several bone marrow failure syndromes such as Fanconi anemia." (PMID 39408846, 2024). "GO and KEGG analysis revealed that the DE mRNAs might be involved in the TNF signaling pathway and Fanconi anemia pathway." (PMID 37891516, 2023). "In contrast, HFI-specific genes were enriched for pathways associated with metabolic pathways, pyrimidine metabolism, NOD-like receptor signaling pathway, DNA replication, purine metabolism, the Fanconi anemia pathway, the TNF signaling pathway, and fatty acid biosynthesis (Q < 0.001)." (PMID 34415987, 2021). "Consistently, analysis of a mouse model of Fanconi anemia, another inherited bone marrow failure syndrome with defective DNA repair, showed that TNF-α exposure creates an environment for clonal selection of somatically mutated preleukemic stem cells, thus leading to leukemogenesis." (PMID 33348919, 2020). "Furthermore, together with HSP40, HSP70 inhibits tumor necrosis factor-α (TNF-α)-induced neuronal cell death by interacting with Fanconi anemia complementation group C, which inhibits interferon-inducible dsRNA-dependent protein kinase, a pro-apoptotic protein." (PMID 34361072, 2021). "Fanconi-anemia, RNA degradation, regulators of NOTCH signaling, and TNF signaling were all allelically suppressed." (PMID 31923184, 2020). "KEGG pathway analysis showed significant enrichment in pathways such as the cell cycle, TNF signaling, NF-kappa B signaling, PI3K-Akt signaling, IL-17 signaling, NOD-like receptor signaling, Toll-like receptor signaling, Fanconi anemia pathway, and chemokine signaling." (PMID 40661083, 2025).